ENTPD7 (ectonucleoside triphosphate diphosphohydrolase 7)
Description:
Catalyzes the hydrolysis of nucleoside triphosphates and diphosphates in a calcium- or magnesium-dependent manner. Preferentially hydrolyzes nucleoside 5'-triphosphates, with substrate preference for UTP > GTP > CTP. Hydrolyzes ATP and nucleoside diphosphates only to a minor extent.
Synonyms: LALP1; FLJ30978
Tractability: Antibody: UniProt predicts a signal peptide or a membrane-spanning region. PROTAC: ubiquitination databases record sites on it; its protein half-life has been measured.
Gene: Protein-coding gene on chromosome 10 (99,659,415 to 99,711,241, forward strand). Ensembl gene ENSG00000198018.
Subcellular location: Cytoplasmic vesicle membrane
Subcellular location (Human Protein Atlas): Nucleoplasm
Pathways (Reactome):
Metabolism: Phosphate bond hydrolysis by NTPDase proteins
Gene Ontology:
Molecular function: CTPase activity; GTPase activity; ribonucleoside triphosphate phosphatase activity; GDP phosphatase activity; UDP phosphatase activity; hydrolase activity
Biological process: CTP catabolic process; GTP metabolic process; nucleobase-containing small molecule catabolic process; UTP catabolic process; CTP metabolic process; UDP catabolic process; purine ribonucleotide metabolic process; pyrimidine ribonucleotide catabolic process; regulation of immune response; T-helper 17 cell differentiation
Cellular component: cytoplasmic vesicle membrane; endocytic vesicle membrane; Golgi apparatus; membrane
Genetic constraint (gnomAD): Loss-of-function variants: 49 observed, 76.44 expected, observed/expected ratio (o/e) 0.64, 90% interval 0.51 to 0.81. The upper end of that interval is the gene's LOEUF score, 0.81, which puts it in group 3 of 6, group 1 being the genes least tolerant of losing a copy. Missense variants: 624 observed, 765.69 expected, observed/expected ratio (o/e) 0.81, 90% interval 0.76 to 0.87. Synonymous variants: 246 observed, 282.06 expected, observed/expected ratio (o/e) 0.87, 90% interval 0.79 to 0.97.
Homologues: Orthologues: macaque ENTPD7 (99% identical), chimpanzee ENTPD7 (99% identical), dog ENTPD7 (97% identical), pig ENTPD7 (96% identical), guinea pig ENTPD7 (95% identical), rabbit ENTPD7 (94% identical), rat Entpd7 (93% identical), mouse Entpd7 (92% identical), tropical clawed frog entpd7 (69% identical), Caenorhabditis elegans mig-23 (30% identical), Caenorhabditis elegans ntp-1 (29% identical). Paralogues in human: ENTPD4 (63% identical), ENTPD2 (23% identical), ENTPD8 (21% identical), ENTPD3 (21% identical), ENTPD1 (21% identical), ENTPD6 (21% identical), ENTPD5 (20% identical).
Diseases named in the same sentence as ENTPD7 in open-access papers:
ENTPD7 is named in the same sentence as 7 diseases in open-access papers, as found by Europe PMC text mining. Sharing a sentence is not in itself a finding about the gene and the disease. The quoted sentences say what the papers report.
glioblastoma (2 papers, 2022). The most malignant astrocytic tumor (WHO grade IV). "When circ-ENTPD7 expression levels were elevated in glioblastoma patients, Kaplan–Meier analysis revealed a low overall survival." (PMID 35883576, 2022). "In glioblastoma tissues, circ-ENTPD7 (hsa-circ-0019421) expression was increased." (PMID 35883576, 2022). "Circ-ENTPD7 silencing decreased glioblastoma cell motility and growth." (PMID 35883576, 2022). "The oncogenic role of circular RNA ENTPD7 (circENTPD7) in cancer biology has been reported in glioblastoma, while its role in non-small cell lung cancer (NSCLC) is unknown." (PMID 35993557, 2022). "Additionally, circ-ENTPD7 worked as a sponge for miR-101-3p, regulating ROS1 expression and promoting glioblastoma cell proliferation and motility." (PMID 35883576, 2022).
liver cancer (2 papers, 2016 to 2019). An epithelial or non-epithelial malignant neoplasm that arises from the liver. "Study found that ectonucleoside triphosphate phosphohydrolase-7 (ENTPD7) played an important role in inhibiting cellular senescence in liver cancer." (PMID 31443651, 2019). "Interestingly, a significant correlation exists between the expression levels of ENTPD7 and ARID1B in several cancer types, including liver cancer." (PMID 27737960, 2016).
bipolar disorder (1 paper, 2023). A disorder of the brain that causes unusual shifts in mood, energy, activity levels and the ability to carry out day-to-day tasks. "A significant difference in the NSAF value in patients with bipolar disorder and healthy individuals was also shown for ectonucleoside triphosphate diphosphohydrolase 7 (ENTPD7)." (PMID 37894929, 2023).
lung carcinoma (1 paper, 2019). "Our data demonstrated that down-regulation of ENTPD7 regulated the proliferation and apoptosis of lung cancer cells by modulating cell cycle-associated and apoptosis-related proteins." (PMID 31443651, 2019). "SP staining results showed that the expression level of ENTPD7 in lung cancer tissues was higher than that in adjacent tissues." (PMID 31443651, 2019). "The aim of this study was to investigate the effects and mechanisms of ectonucleoside triphosphate phosphohydrolase-7 (ENTPD7) on lung cancer cells." (PMID 31443651, 2019). "The expression characteristics of ENTPD7 and its effect on the survival of lung cancer patients were analyzed by referring to The Cancer Genome Atlas (TCGA)." (PMID 31443651, 2019). "Tumor-bearing nude mice experiments showed that silencing ENTPD7 had an inhibitory effect on lung cancer cells." (PMID 31443651, 2019). "SP staining results also showed that ENTPD7 had a higher expression level in lung cancer tissues than that in adjacent tissues." (PMID 31443651, 2019). "We first determined the expression characteristics of ENTPD7 in lung cancer tissues by using clinical samples." (PMID 31443651, 2019). "The expression level of ENTPD7 in different lung cancer cell lines was detected by qRT-PCR and Western blot." (PMID 31443651, 2019). "Down-regulation of the expression of ENTPD7 inhibited proliferation but promoted apoptosis of lung cancer cell." (PMID 31443651, 2019). "This suggested that the ENTPD7 gene was up-regulated in lung cancer tissues and cells." (PMID 31443651, 2019). "This demonstrated that the inhibition of ENTPD7 might inhibit lung cancer cell proliferation and promote apoptosis by down-regulating protein expression and phosphorylation of the protein in the Ras/Raf/MEK/ERK pathway." (PMID 31443651, 2019). "Furthermore, the results also showed that the mRNA and protein levels of ENTPD7 in the five lung cancer cell lines were significantly higher than those in normal lung epithelial cells, showing that ENTPD7 was overexpressed in lung cancer tissues and cells." (PMID 31443651, 2019). "Down-regulating ENTPD7 could inhibit lung cancer cell proliferation and promote apoptosis via inhibiting the Ras/Raf/MEK/ERK pathway." (PMID 31443651, 2019). "Therefore, this study mainly explored the expression characteristics of ENTPD7 in lung cancer, the effects of ENTPD7 on the proliferation and apoptosis of lung cancer cells and the mechanism of action." (PMID 31443651, 2019). "Moreover, by conducting bioinformatics research, we found that ENTPD7 levels in lung cancer patients at different TNM stages were different, and the survival analysis showed that lung cancer patients with a low level of ENTPD7 had a higher survival rate." (PMID 31443651, 2019). "However, to the best of our knowledge, no research has been conducted on the role of ENTPD7 in lung cancer." (PMID 31443651, 2019). "In conclusion, ENTPD7 was overexpressed in lung cancer tissues and cells, and the inhibition of ENTPD7 had the effects of inhibiting lung cancer cell proliferation and promoting apoptosis of lung cancer cells, and this might be related to the inhibition of Ras/Raf/MEK/ERK induced by ENTPD7." (PMID 31443651, 2019).
Sepsis (1 paper, 2020). Sepsis is defined as life-threatening organ dysfunction caused by a dysregulated host response to infection. "There are few shared hub-associated entities between adult and pediatric Sepsis, with the exception of GPR84-associated EXOSC4 and ENTPD7, CD177-associated DDAH2 and MYL9-associated TGFB1l1." (PMID 32318053, 2020). "Gene entities shared between sepsis and severe sepsis response hubs are; TDRD9 – LIN7A, GPR84 – ENTPD7, PYCT1A and ZDHHC19, CD177 – DDAH2 and RGL4, SLC16A3 – DENND3 and MBD6, MYL9 – CMTM5, ITGB3, ITGA2B, NRGN, SELP and TREML1." (PMID 32318053, 2020).
tumor (1 paper, 2019). "Streptavidin-peroxidase (SP) staining was performed to detect the ENTPD7 protein in tumor tissues and adjacent tissues." (PMID 31443651, 2019). "The analysis showed that the mRNA expression levels of ENTPD7 were different in tumor tissues of patients at different TNM stages." (PMID 31443651, 2019).
ENTPD7 also shares sentences with these, for which no sentence is quoted: cancer (2 papers).